TNF (tumor necrosis factor)
Diseases named in the same sentence as TNF in open-access papers (continued):
Sharing a sentence is not in itself a finding about the gene and the disease.
COVID-19 (continued). "This study aimed to evaluate the association of the levels of cytokines interleukin (IL)-2, IL-6, tumor necrosis factor-alpha (TNF-α), interferon-gamma (IFN-γ), and IL-10 with the severity of COVID-19 in Bangladesh." (PMID 38707035, 2024). "A comparative analysis of patients diagnosed with COVID-19, COVID-19 with concurrent maculopapular rash, or DRESS found that there were similar elevations of CXCL9, CXCL10, CXCL11, IFN-γ, IL-10, TNF-α, and IL-18 across the three groups." (PMID 39318634, 2024). "Interleukins, such as interleukin-6 (IL-6) and tumor necrosis factor-alpha (TNF-α), play an important role in lung damage in COVID-19 patients through impairment of the respiratory epithelium." (PMID 39065742, 2024). "High levels of these molecules, detected after macrophage treatment with VLPs (TNFα, IL-1β, CCL8, CXCL8, CXCL9, CXCL16, CXCL1, and CXCL2), were shown to correlate with severe COVID-19 in other studies." (PMID 38664730, 2024). "Another factor to consider is that the TNF-α and NF-κB pathways are related to ROMO1, COVID-19, and oxidative stress." (PMID 38622314, 2024). "Based on the associated molecular mechanisms, combined inhibition of IFN-γ and TNF-α, along with JAK-STAT pathway inhibitors and iNOS inhibitors, presents a novel therapeutic approach for the prevention and treatment of severe COVID-19." (PMID 39560514, 2024). "COVID-19 patients with CVD who were taking statins had significantly lower median concentrations of IL-6 (21 vs. 44 pg/mL, p = 0.027), TNFα (21 vs. 39.5 pg/mL, p = 0.036), and IL-10 (19 vs. 25.5 pg/mL, p = 0.025) compared to COVID-19 patients with no CVD." (PMID 39518552, 2024). "Elevated IL-6 levels contribute to severe lung damage, and both IL-6 and TNF-α play crucial roles in cytokine storm, ARDS, and mortality in COVID-19 patients." (PMID 38568894, 2024). "A weighted gene co‐expression network analysis (WGCNA) of RNA-sequencing dataset revealed four key genes, PROK2, IL6, TNF, SLC7A11, closely related to COVID-19 ALI41." (PMID 38769293, 2024). "Many cytokines have been reported at elevated levels in COVID-19 cases, including IL1-β, IL-6, IL-7, IL-8, TGF-β and TNF-α." (PMID 38914619, 2024). "Among the many cytokines with significantly greater cumulative exposure in COVID-19 were CXCL10, CCL8, CCL2, IL-6, and TNF-α (q < 0.05, Mann-Whitney)." (PMID 38502186, 2024). "The top ten anti-COVID-19 core targets, AKT1, TNF, HSP90AA1, IL-6, mTOR, EGFR, CASP3, HIF1A, MAPK3, and MAPK1, were chosen for molecular docking studies with the Meliae cortex’s key active phytonutrients determined in section 3.7." (PMID 36817449, 2023). "In contrast, studies consistently find increased proinflammatory cytokines such as tumor necrosis factor (TNF), IL-6, and chemokines in severe COVID-19 patients." (PMID 37361874, 2023). "We also assessed the proinflammatory cytokine (TNF-α, IL-6, and IL-1β) levels in RBD-treated cells as COVID-19 leads to a cytokine storm." (PMID 36982738, 2023). "In severe cases of COVID-19, multiple studies have indicated higher levels of IL-2, IL-6, IL-7, IL-10, CXCL10(IP-10), CCL2 (MCP-1), TNF-α, CCL3(MIP-1α), and G-CSF when compared to patients with mild and moderate infections." (PMID 37834246, 2023). "This study aimed to evaluate the levels of immunological biomarkers such as CRP, C3, C4, IL-8, IL-10, IL-12, TNF-α, and IFN-γ in patients with COVID-19 and bacterial pneumonia." (PMID 38585537, 2023). "The key targets in the PPI network also present in the “Coronavirus disease - COVID-19” pathway included IL6, MAPK1, JUN, F2, and TNF." (PMID 38050310, 2023). "The most relevant cytokines that were significantly associated with acute respiratory distress syndrome (ARDS) by COVID-19 were: MCP-3, TNF-α, fractalkine/CX3CL1, M-CSF, and MCP-1/CCL2." (PMID 36851766, 2023).
COVID-19 (continued). "In response to SARS-CoV-2 S-RBD and SARS-CoV-2 ICL, we observed significantly increased frequencies of CD8+ T cells expressing IFN-γ, IL-2, TNF-α, and IL-17A in MIS-C compared to children with COVID-19 and other infectious diseases." (PMID 38116577, 2023). "Our results showed that COVID-19 patients had significantly higher levels of IFN-γ, TNF, IL-1β, IL-2, IL-6, IL-8, and IP-10 than the unexposed group." (PMID 37018291, 2023). "In the severe forms of COVID-19 and many other infectious diseases, the patients develop a cytokine storm syndrome (CSS) where pro-inflammatory cytokines such as IL-6 and TNF-α play a key role in the development of this serious process." (PMID 37951972, 2023). "Among these connections, ADHD exerts a promotion effect on COVID-19 through the inhibition of OXT and PON1 and the promotion of CRP, AR, and TNF." (PMID 38066446, 2023). "At baseline, for non-KTRs, differences in several cytokines and vascular mediators were observed when the COVID-19 patients were compared with the HCs, except for ADAMTS-13, myoglobin, IL-9, G-CSF, and TNF-α." (PMID 38005844, 2023). "It was reported that COVID-19 patients exhibited high plasma levels of C-C motif chemokine ligand 2 (CCL2), CXCL10, IFN-γ, IL-1β, IL-7, IL-8, IL-10 and TNF-α." (PMID 37251383, 2023). "The study revealed a pattern of decreased expression of DNMT genes (DNMT3A and DNMT3B) and an increase in the methylation of the TNF-α and TLR4 promoters in COVID-19 patients, as well as a correlation between global methylation and disease severity." (PMID 36840831, 2023). "Serum pro-inflammatory cytokines, including IL-6, TNF-α, IL-1β, and IFN-γ, are dramatically elevated in critical COVID-19 patients and identified as markers of poor prognosis." (PMID 36717892, 2023). "The data shows that cytokines like IL-6, TNF-a, and IL-1β are produced by both the influenza virus and SARS-CoV-2, though levels are higher in COVID-19 patients." (PMID 37200377, 2023). "The study also measured proinflammatory cytokines and chemokines in the semen, including IL-6, tumor-necrosis-factor (TNF), and CCL2 (MCP-1), and COVID-19 patients had significantly higher levels than the control group." (PMID 37457430, 2023). "The network of enriched term by clusters is involved in cytokine signaling in the immune system, TNF signaling, response to growth factor, regulation of MAPK cascade, positive regulation of cellular components, COVID-19, and so on." (PMID 37006463, 2023). "Markers of hyperinflammation, degree of lymphopaenia, neutrophil levels, TNF-α, INR levels, and proinflammatory cytokines (interleukin (IL)-6 and IL-8) were significantly increased in COVID-19 patients compared to healthy controls (p < 0.05, 95% CI)." (PMID 37731491, 2023). "By using canonical correlation analysis (CCA), the gut microbiota composition of 30 patients with COVID-19 was visualized by prognostic groups with five serum cytokines – IFN-γ, IL-2, IL-10, TNF-α, and anti-SARS-CoV-2 S immunoglobulin G (IgG) titers." (PMID 37051240, 2023). "At baseline, there were significantly increased frequencies of CD4+ T cells expressing IFN-γ IL-2, TNF-α, and IL-17A in MIS-C compared with children with COVID-19 or with other infectious diseases." (PMID 38116577, 2023). "The COVID-19 group had significantly higher levels of IFN-γ (P<0.01), IL-2 (P<0.01), IP-10 (P<0.01), IL-1β (P = 0.001), IL-6 (P = 0.002), IL-8 (P = 0.003), and TNF (P = 0.014) when compared to the unexposed healthy group." (PMID 37018291, 2023). "Results showed that patients with COVID-19 who were admitted to intensive care units had higher concentrations of CXCL10, CCL2, and TNF-α compared to that in patients with milder infections." (PMID 37363730, 2023). "Another proteomic-based study involving COVID-19 patients reported high levels of RIG-I, TNF-α, and IL1R in liver tissues, indicating liver injury and expression of these biomarkers mediating the NF-κB pathway." (PMID 36671484, 2023).
COVID-19 (continued). "The authors also identified six COVID-19-related discriminant cytokines including Interleukins (IL)-2, 5, 6, Granulocyte colony-stimulating factor (GCSF), Tumor necrosis factor-α (TNF- α), and Interferon-γ (IFN- γ), but only IL-12 for controls." (PMID 37174613, 2023). "The antiviral IFN-α and proinflammatory TNF, IL-6, IL-8, IL-17, IL-33, and IFN-γ were elevated in COVID-19 patients at both time points, while IL-10 and IL-1β were increased at admission and one week later, respectively." (PMID 37174682, 2023). "The main potentially acting signaling pathways include the interleukin (IL)-17 signaling pathway, tumor necrosis factor (TNF) signaling pathway, Toll-like receptor signaling pathway, Th17 cell differentiation, and coronavirus disease-COVID-19." (PMID 36701702, 2023). "MVPA also modulated the peripheral frequency of Treg cells and the expression of PD-1 in CD8+ T cells, although it abrogated the statistical effect in the analysis of TNF-α and IL-6 production by LPS- and PMA-stimulated PBMC of post- COVID-19 patients." (PMID 37753077, 2023). "The top three Meliae cortex’s key active phytonutrients were further analyzed for molecular docking with the top ten anti-COVID-19 core targets, including AKT1, TNF, HSP90AA1, IL-6, mTOR, EGFR, CASP3, HIF1A, MAPK3, and MAPK1." (PMID 36817449, 2023). "Five inflammatory markers were evaluated in the present study, IL-6, IL-8, IL-10, TNF-α, and CRP in hospitalized COVID-19 patients." (PMID 37111039, 2023). "The top 10 of 41 potential anti-COVID-19 core targets (AKT1, TNF, HSP90AA1, IL-6, mTOR, EGFR, CASP3, HIF1A, MAPK3, and MAPK1) were identified as molecular targets of key active phytonutrients of the Meliae cortex that might be implicated in ameliorating COVID-19." (PMID 36817449, 2023). "The cytokines TNF-α, IFN-γ, IL-6, IL-2, and IL-10 quantified in newborns of mothers with COVID-19 showed high levels of expression compared with the control group." (PMID 36979888, 2023). "Patients with severe COVID-19, as evidenced in our study, release a large amount of pro-inflammatory cytokines (IFN-α, IFN-γ, IL-1β, IL-6, IL-12, IL-18, IL-33, TNF- α, and TGF- β)." (PMID 37408032, 2023). "Dexamethasone, by targeting the glucocorticoid receptor is able to modulate COVID-19-evoked ARDS through pathways with wide effects on inflammatory factors, such as NF-κB, IL-1β, TNFα and IL-6, as well as fibrosis." (PMID 36791125, 2023). "In severe COVID-19 cases, IFN-I response arouses an excessive inflammatory response by promoting TNF/IL-1β-driven inflammation leading to cytokine storm." (PMID 36949448, 2023). "Transcriptome profiling of in vitro models of the airway epithelium revealed increased expressions of IL-1β, TNF-α, CCL2, CCL20, CCL8, CXCL2, CXCL8, and CXCL16 (all of which are upregulated in severe COVID-19), resulting in lung injury and multiorgan failure." (PMID 37631998, 2023). "Among all COVID-19 patients, significantly higher levels of IFN-α, IL-6, or TNF-α were shown in serum samples from the Hispanic patients compared with those from the Chinese patients." (PMID 36810114, 2023). "The aim of this study was to investigate the predictive utility of interleukin (IL)-6, IL-8, IL-10, IL-12, tumor necrosis factor alpha (TNF-α), and interferon gamma (IFN-γ) measurement in patients with COVID-19." (PMID 37969879, 2023). "AMP, along with the daily practice of SKY, during normal life (pre-COVID-19 phase) reduced mRNA expression of IL1β, IL6, and TNF and increased mRNA expression of SOD, catalase, and GPx." (PMID 37546047, 2023). "Severe patients (n = 6) showed a significant increase in a subset of plasma cytokine/chemokine levels (IL-2, IL-4, IL-6, IL-8, MIP-1β, and TNF-α; ANOVA, p adjusted <0.05 to <0.001) in comparison with the pauci COVID-19 patients (n = 8) and/or controls." (PMID 37047752, 2023).
COVID-19 (continued). "The most prevalent module for genes resulting from this classifier were indicative of a high TNF response in COVID-19 ICU patients and high expression of TNF family members has been found in damaged tissue of COVID-19 patients indicative of severe disease." (PMID 36902333, 2023). "The proinflammatory proteins with the highest expressions in COVID-19 patients included: CXCL11, PD-L1, TNF, IL6, MCP3, CXL10, C XCL23, IL6 and IL8; p < 0.05." (PMID 37832397, 2023). "The lungs of patients with severe COVID-19 are abundant in highly inflammatory macrophages, which secrete inflammatory mediators like IL-1β, IL-6, IL-8, CXCL10, TNF-α, and other chemokines, further exacerbating the occurrence of cytokine storms." (PMID 37163438, 2023). "Consistent with our findings in TB patients, prior COVID-19 led to reduced levels of IFN-γ, IL-1β, IL-7 and TNF-α in ORD patients." (PMID 38179046, 2023). "TNFα and IFNγ induce PANoptosis in mice that leads to CSS and death, which has been suggested to mimic severe COVID-19 in patients." (PMID 37459541, 2023). "The increased expression of TNF-α, NF-kB, VEGF, VEGFR-1, GJA-1 (Connexin-43), and CTNNB-1 (β-catenin) in the COVID-19 group suggests a strong activation of angiogenic pathways in response to hypoxia and hyperinflammation associated with SARS-CoV-2 infection." (PMID 36992415, 2023). "Calcineurin inhibitors were discontinued by 40%, thiopurines by 31.6%, anti-TNFα antibodies by 24.5%, vedolizumab by 15.7%, JAK inhibitors by 15.4%, and ustekinumab by 13.1% of patients after the COVID-19 diagnosis." (PMID 39131552, 2023). "Along with the upregulation of inflammatory mediators such as IL1B, TNF, and IL6, the downregulation of CCL5 can be a major contributor to COVID-19-mediated neuroinflammation." (PMID 37686360, 2023). "The levels of many proinflammatory cytokines (IL-1β, IL-6, IL-8, IL-17, TNF, G-CSF, GM-CSF) and chemokines (IP10, MCP1, MIP1α), were elevated in COVID-19 patients, with higher levels in critically ill subjects." (PMID 36672688, 2023). "The blood concentrations of the antiviral cytokine IFN-α and proinflammatory cytokines TNF, IFN-γ, IL-6, IL-8, IL-17, and IL-33 were significantly increased in COVID-19 patients both at admission and one week later, compared to healthy controls." (PMID 37174682, 2023). "Most patients with severe COVID-19 show higher levels of serum pro-inflammatory cytokines such as IFN-α, IFN-γ, IL-6, IL-12, and TNF-α." (PMID 37799713, 2023). "In particular, in TB-COVID-19 co-infected patients TNF-α, MIP-1β, and IL-9 showed significant elevated levels compared to COVID-19 only, and TNF-α had the highest discriminant power." (PMID 37662901, 2023). "COVID-19 patients produced lower TNF-α, 62 times lower with LPS and 83 times lower with LPS + rhIFN-γ than healthy subjects (TNF-α pg/mL, median = LPS: 27 vs. 1671, and LPS + rhIFN-γ: 20 vs. 165, patients vs. healthy controls)." (PMID 37189696, 2023). "The inhibition of cell death pathways mediated by TNF-α and IFN-γ to reduce tissue damage and inflammation is an adjuvant therapy for COVID-19 and other inflammatory diseases." (PMID 37405258, 2023). "Compared to HCs, a significant increase in IL-23, IL-10, TNF-α, IFN-γ and MCP-1, were observed in COVID-19 patients." (PMID 37283736, 2023). "RNA sequencing data of COVID-19 subjects showed higher expression of the endothelia cell activation markers RELB and TNF-α." (PMID 37626992, 2023). "COVID-19 patients and those with liver injury exhibit clinical manifestations, including elevation in ALT, AST, GGT, bilirubin, TNF-α, and IL-6 and reduction in the levels of CD4 and CD8." (PMID 36671484, 2023). "The majority of SARS-CoV-2-specific CD4+ T cells from COVID-19 patients show a clear IFN-γ, tumor necrosis factor (TNF) and IL-2 protein signature characteristic of canonical Th1 cells." (PMID 36776863, 2023).
COVID-19 (continued). "A handful of studies have explored the measurement of biomarkers NfL, GFAP, tau proteins, IL-6, IL-10, TNF-α, and CPR during acute COVID-19 and PASC." (PMID 37545721, 2023). "The top three biomarkers with the highest potential to differentiate between COVID-19 and the HCs were IL-10, IFN-α, and TNF-α." (PMID 38005844, 2023). "TNF and IL6 showed significant upregulation in COVID-19 patients, while the expression changes of the other targets were relatively minor." (PMID 38050310, 2023). "Patients with inflammatory bowel disease (IBD) receiving anti-TNF and JAK-inhibitor therapy have attenuated responses to COVID-19 vaccination." (PMID 37842172, 2023). "PPI network and core target analysis indicated that IL-6, TNF, MAPK1, and IL1B were the key targets against COVID-19." (PMID 38018195, 2023). "The cytokine profile involved in the pathogenesis of lung damage in COVID-19 is similar to that observed in the pathogenesis of joint damage in RA, with IL1, IL6 and TNF-α as key players." (PMID 37564642, 2023). "In this study we found persistent elevation of multiple mediators – IL-6, TNFα, SAA, Tie-2, Flt1, PIGF, and CRP – and persistent depression of IL-7 and bFGF in patients recovering from COVID-19 several months following their acute infection." (PMID 36844209, 2023). "The up-regulated cytokines (IFN-γ, TNF-α, IL-6, IL-10) in our study indicate induced activation of immune responses against SARS-COV-2 infection and are consistent with other COVID-19 studies." (PMID 38057707, 2023). "Early reports of COVID-19 showed elevated levels of pro-inflammatory cytokines, e.g., IL1b, TNF and IL6, especially among severe COVID-19 cases, implicating a cytokine-storm process." (PMID 36829233, 2023). "Altogether, eight biomarkers stood out as the main inflammatory mediators with discriminative potential between the COVID-19 (recovered/long-COVID-19) and healthy unexposed groups: IFN-γ, IL-10, IL-6, IL-2, IP-10, TNF, IL- 1β, and IL-8." (PMID 37018291, 2023). "Gene set enrichment analysis of DEGs showed upregulation of IL-18 (P < 0.001), TNF (P < 0.0001), and VEGFA-VEGFR2 signaling pathways (P = 0.002) in COVID-19 subjects." (PMID 36881624, 2023). "Measurement of serum levels of IL-10, TNF-α, INF-γ and TLR-4 showed a highly significant increase in their levels in the COVID-19 patients compared to controls (P value = 0.0001*)." (PMID 36864077, 2023). "Interestingly, recent improvements in the pathophysiologic understanding of COVID-19 revealed that the severity of COVID-19 is strongly associated with cytokine release syndrome (CRS), which is characterized by elevated tumor necrosis factor (TNF-α), interleukin (IL)-6, IL-2, IL-7, and IL-10." (PMID 36770606, 2023). "In a small cohort of seven MIS-C patients, differentiation between COVID-19 and MIS-C patients was achieved using a combination of IL-10, IL-1RA, IL-18, IL-6, TNF and IFN-gamma." (PMID 37685502, 2023). "More specifically, and according to our models, dexamethasone is able to modulate COVID-19 evoked ARDS through pathways with wide effects in inflammation, such as those activated by NF-κB, IL-1β and TNFα." (PMID 36791125, 2023). "This means that the body avoids a prolonged inflammatory response and its damaging effects since it is known that there is increased expression of pro-inflammatory cytokines IL–1β, IL–6, TNF, IL–12, IFN–β, IFN–γ, IL–17 in COVID-19." (PMID 36833234, 2023). "Although the IL6 gene is not among the top 20 DEGs, it is noteworthy that it is over-expressed downstream to several signaling pathways, like TNF, IL17, C-type lectin receptors, and COVID-19 disease KEGG pathways." (PMID 38003837, 2023). "Clinical evidence suggests that patients with severe COVID-19 have markedly increased levels of pro-inflammatory cytokines within their bodies, including IL-1β, IL-2, IL-6, IL-7, IL8, TNF-α, CCL2, MIP-1α, and CXCL10." (PMID 37163438, 2023).